EGFR (epidermal growth factor receptor)
Diseases named in the same sentence as EGFR in open-access papers (continued):
Sharing a sentence is not in itself a finding about the gene and the disease.
breast carcinoma (continued). "Analysis of EGFr and ER was performed on tumour samples from 231 patients with operable breast cancer followed for up to 6 years after surgery." (PMID 1846551, 1991). "Breast cancer and lung adenocarcinoma share common features, including female predominance and the expression of estrogen receptor (ER) and epidermal growth factor receptor (EGFR) during carcinogenesis." (PMID 41597172, 2026). "Thus, we tested the surface expression levels of HER2, as well as EpCAM and EGFR, by staining four breast cancer cell lines with these markers individually, as well as in a cocktail." (PMID 41543394, 2026). "In breast cancer, this pathway is frequently hyperactivated due to PIK3CA mutations, loss or inactivation of the tumor suppressor PTEN, and hyperactivation of upstream receptor tyrosine kinases (RTKs) such as HER2 and epidermal growth factor receptor (EGFR)." (PMID 41510186, 2026). "Also overexpression of EGFR or the high activity of EGFR signal pathway has been related in breast cancer patients with increases in cell proliferation." (PMID 41521222, 2026). "According to the RT-qPCR results, the hub genes SRC, PIK3CA, and EGFR may be involved in the anti-breast cancer effects of TSAC." (PMID 40864816, 2025). "However, the detection of EGFR overexpression in breast cancer primarily relies on invasive procedures, which can increase patient discomfort, procedural risks, and overall testing costs and complexity." (PMID 41179692, 2025). "Likewise, EGFR overexpression in breast cancer cells increases lactate production, and inhibition of EGFR tyrosine kinase signalling decreases lactate production and basal ECAR in NSCLC cells." (PMID 39433211, 2025). "EGFR amplification was found in 5.1% of the breast cancers profiled." (PMID 40501689, 2025). "Overexpression of epidermal growth factor receptor(EGFR) has been consistently observed in many human epithelial cancers, including gastric, colorectal, bladder, pancreatic, ovarian, lung, and breast cancers, making EGFR a validated target for cancer diagnosis and therapy." (PMID 41325799, 2025). "Additionally, other pathways, including EGFR/HER2 signaling in breast cancer, can activate the RAS pathway, further hyperactivating macropinocytosis as a cancer‐specific uptake mechanism." (PMID 39951277, 2025). "Malignant basal-like breast tumors represent approximately 15% of all diagnosed cases of breast cancer, have high proliferation rates, and exhibit high expression of basal cytokeratins and epidermal growth factor receptor (EGFR), along with low expression of the luminal A genetic signature." (PMID 41516015, 2025). "Recent studies have shown that WZ4003 may play a role in the pathogenesis of breast cancer by inhibiting the EGFR signaling pathway." (PMID 40666073, 2025). "In addition, E2 signaling to ERK 1/2 was dependent upon the transactivation of the EGFR via the release of membrane-associated heparin-bound EGF (HB-EGF) in MDA-MB231 cells, which are ER- breast cancer cells." (PMID 40422206, 2025). "Clinical evidence indicates that EGFR overexpression is linked to poorer prognosis and adverse outcomes in aggressive TNBC patients, while IGF-IR is overexpressed in varying degrees across breast cancer subtypes." (PMID 40943584, 2025). "Likewise, in certain cancer subtypes, circRNA CDR1as can sequester miR-7, resulting in dysregulated EGFR expression and leading to resistance to targeted therapies in lung and breast cancers." (PMID 41281941, 2025). "Resistance to EGFR–tyrosine kinase inhibitor (EGFR-TKIs) therapies in breast cancer presents a significant clinical challenge, with the mechanisms of this resistance remaining largely unknown." (PMID 40560045, 2025). "Furthermore, blocking nEGFR promotes NK cell infiltration into the tumors of an EGFR-dependent breast cancer mouse model." (PMID 39521886, 2025).
breast carcinoma (continued). "Furthermore, suppressing the AREG/EGFR signaling pathway can be a fundamental therapeutic strategy for EGFR+ and ER+ breast cancers when combined with classic chemotherapy." (PMID 40422206, 2025). "In breast cancer, ligand-dependent activation of EGFR can contribute to resistance." (PMID 40560045, 2025). "This study successfully identified TSAC’s serum-absorbed bioactive components and demonstrated their anti-breast cancer effects via multi-target mechanisms involving the Src/PI3K/EGFR axis, providing a crucial pharmacological foundation for developing A. chinensis-derived breast cancer therapies." (PMID 40864816, 2025). "Notably, cetuximab restored tumor sensitivity to fulvestrant and abemaciclib in FAR- and EGFR-overexpressing breast cancer spheroids and xenografts." (PMID 40244377, 2025). "Based on these results, we hypothesized that E2-induced AREG expression mediated the cell proliferation, growth, and tumorigenicity of ER+ breast cancer cells by activating the EGFR." (PMID 40422206, 2025). "Therefore, the induction of AREG by E2 plays an important role in cell proliferation and migration in EGFR+ and ER+ breast cancer cells." (PMID 40422206, 2025). "Studies in the literature on the anti-cancer effects of EGFR inhibitor drugs related to breast cancer on MDA-MB-231 cells have reported IC50 concentrations of 20.7 μM for gefitinib, 42.6 μM for erlotinib, 15.4 μM for carboplatin, 59.6 nM for doxorubicin, and 3.0 nM for docetaxel." (PMID 41226241, 2025). "EGFR expression varies between breast cancer subtypes and ethnic groups." (PMID 40417193, 2025). "Such aberrant EGFR phosphorylation, caused by direct crosstalk between EGFR and other receptor tyrosine kinases or indirectly with the help of Src creating docking sites for EGFR interaction, is considered a mechanism leading to intrinsic resistance of breast cancer to EGFR TKIs." (PMID 40560045, 2025). "Total cell protein was subjected to Western blotting probed with a phospho-Y1068 specific antibody, and revealed substantial inhibition of EGFR phosphorylation at Y1068 in the bladder cancer cell lines and slightly less inhibition in the breast cancer cell lines." (PMID 40754248, 2025). "Moreover, the physical interaction between wt-EGFR and AKT has been implicated in gefitinib resistance in breast cancer." (PMID 41514577, 2025). "Epidermal growth factor receptor (EGFR) is pivotal in modulating the advancement of breast cancer." (PMID 40929235, 2025). "In a different study, miR-218-5p was found to have supported the ERBB2 and EGFR expression by inhibiting the LRIG1 in breast cancer cells, which shows that miR-218-5p, and LRIG1can act as an oncogene in breast cancer and can be used as a therapeutic target for breast cancer treatments." (PMID 38954213, 2025). "In a parallel study (unpublished data) conducted by our research group, we observed that Fz25 (IC50 of 8.13 ± 0.15) and Fz57 (IC50 of 11.94 ± 0.19) were cytotoxic against MCF-7 (ER + and EGFR -) breast cancer cells comparable to sorafenib, positive control (IC50 of 12.21 ± 0.96)." (PMID 39942711, 2025). "Conversely, an anti-CD73 antibody could inhibit breast cancer cell motility by modulating autophagy, whereas EGFR inhibitors induce autophagy, promoting drug resistance." (PMID 40191718, 2025). "To determine whether our findings on HLA-A, -B, and -C extend beyond MDA-MB-231 cells, we examined the synaptic abundance of these molecules in MDA-MB-468 cells, a more epithelial-like and EGFR-dependent breast carcinoma cell line." (PMID 40763024, 2025). "Additionally, docking estimations were accomplished to anticipate the docking pose and score of the DAMNI against ERα and EGFR, which are recognized for their roles in breast cancer treatment." (PMID 40929235, 2025). "EGFR/HER2 activation could be the driving mechanism behind the CSC enrichment in tamoxifen-resistant breast cancer." (PMID 40843360, 2025).
breast carcinoma (continued). "Based on the sandwich ELISA principle, isolated EVs were captured by anti-CD63 modified magnetic beads and subsequently bound by breast cancer-associated markers (EpCAM, PSMA, HER2, EGFR, CEA, CA125) serving as detection probes, with sensing completed via TMB oxidation-induced color change." (PMID 41404198, 2025). "Additionally, in EGFR TKI-resistant breast cancer cell lines, the receptor tyrosine kinase MET plays a role in promoting resistance." (PMID 40560045, 2025). "Notably, FER is key to the rapid endocytic recycling of integrin α6 and β1 in high-grade breast cancer during invasive growth and can dictate endosomal sorting of the epidermal growth factor receptor (EGFR) through tyrosine phosphorylation of PKCδ-Y374." (PMID 41115375, 2025). "Furthermore, suppressing the AREG/EGFR signaling pathway can be a fundamental therapeutic strategy for treating ER+ breast cancer when combined with classical chemotherapy." (PMID 40422206, 2025). "Taken together, EGFR may play a role in the progression of breast cancer and glioma by affecting intercellular communication through Cx43 phosphorylation." (PMID 40416989, 2025). "Additionally, FAS inhibition can disrupt lipid raft assembly and impair EGFR localization to the membrane of breast cancer cells." (PMID 40608162, 2025). "Moreover, EGFR signalling in breast cancer cells increases c-Myc expression, HK2 activity, and GLUT1 plasma membrane localisation, while decreasing expression of TXNIP." (PMID 39433211, 2025). "Notably, plectin is significantly upregulated in inflammatory breast cancer cells exhibiting EGFR+ expression, where it modulates cell migration through the integrin/EGFR signaling axis." (PMID 41011568, 2025). "Notably, by predicting the EGFR expression status, this study expands the application of radiomics to the molecular subtyping of breast cancer." (PMID 41179692, 2025). "However, clinical trials assessing the efficacy of EGFR TKIs in breast cancer have yet to demonstrate significant benefit, despite the frequent occurrence of EGFR overexpression." (PMID 40364160, 2025). "Thus, it is possible that ADAM12 is induced by HIF-1α in SIP, as in breast cancer, and that this induces the EGFR activation pathway." (PMID 41346909, 2025). "The extract moderately inhibited α-glucosidase (IC50 = 110 ± 4.25 μg/mL), suggesting that it has antidiabetic activity, and downregulated Epidermal Growth Factor Receptor (EGFR) expression in a human breast cancer cell line (MCF7), suggesting that it has anticancer effects." (PMID 40733039, 2025). "The hub targets identified for SRC, PIK3R1, PIK3CA, STAT3, and EGFR may represent significant therapeutic targets for the treatment of breast cancer using TSAC." (PMID 40864816, 2025). "Nonetheless, the clinical translatability of these observations is limited by the heterogeneous expression of EGFR in breast cancer and the common emergence of resistance, underscoring the need for robust predictive biomarkers and more advanced preclinical models." (PMID 41373619, 2025). "However, in breast cancer, the response to anti-EGFR therapy has been mixed owing to the diverse phenotypes and inter-tumoral heterogeneity." (PMID 40560045, 2025). "Our results demonstrated that resveratrol markedly decreased phosphorylated ERK1/2 and AKT levels in all tested breast cancer cells, consistent with a reduction in membrane phospholipid synthesis and subsequent disruption of lipid raft assembly and EGFR localization." (PMID 40733158, 2025). "Therefore, in this study, we developed a machine learning-based approach utilizing ultrasound radiomics to non-invasively predict EGFR expression status in patients with breast cancer." (PMID 41179692, 2025). "This study evaluates the interaction between camptothecin, a potent anticancer agent, and two key receptors implicated in breast cancer progression: HER2 (human epidermal growth factor receptor 2) and EGFR (epidermal growth factor receptor), using molecular docking." (PMID 40136447, 2025).
breast carcinoma (continued). "Additionally, the overexpression of EGFR in breast cancer correlates with tumor progression and poor prognosis, making it a critical target for CAR-T cell therapy." (PMID 41409286, 2025). "In basal-like breast cancer, a 2020 study identified associations between key receptors such as Tumor necrosis factor receptors (TNFRs), Transforming growth factor-beta receptor type 1 (TGFBR1), and EGFR, and ELK1." (PMID 40862737, 2025). "Additionally, deregulated expression of EGFR in the inducible form, v-ERb-B:ER gene was shown to confer both chemo- and radio-resistance in breast cancer cells." (PMID 39668367, 2024). "Consequently, EGFR has emerged as a pivotal therapeutic target in cancers such as breast cancer, non-small cell lung cancer, and colorectal cancer." (PMID 39796003, 2024). "Studies suggest that this approach may be effective in treating prostate and breast cancers with nuclear EGFR expression." (PMID 39404930, 2024). "Furthermore, the IHC analysis of EGFR protein levels (left, middle) presented positive staining of all examined breast cancer samples, for which 50% showed high intensity, 42% with medium intensity, and only 8% showed low intensity." (PMID 39707884, 2024). "MPP7 promotes breast cancer aggressiveness via epidermal growth factor receptor signaling." (PMID 39224268, 2024). "Furthermore, combinations such as the EGFR-targeting drug erlotinib with bevacizumab, and cetuximab with cisplatin, have demonstrated substantial benefits in extending the survival time of breast cancer patients and alleviating symptoms, respectively." (PMID 38751788, 2024). "For example, Lamp2b can fuse with an anti-HER2 nanobody and direct exosomes to HER2-overexpressing breast cancer cells, while exosomes displaying anti-EGFR nanobody are found to suppress EGFR signaling and reduce proliferation in triple negative breast cancer cells." (PMID 38172932, 2024). "Our investigation has illuminated a new facet of TSL’s pharmacological profile, revealing its selective anti-proliferative efficacy against breast cancer cells overexpressing estrogen receptor (ER) or human epidermal growth factor receptor 2 (HER2)/epidermal growth factor receptor (EGFR)." (PMID 39906392, 2024). "However, a decrease in EGFR expression was observed in MCF-7 breast cancer cells after 14 days on the RPM." (PMID 39456226, 2024). "Furthermore, the use of EGFR nanobodies displayed on the surface of EVs enhanced their binding affinity for breast cancer." (PMID 38543204, 2024). "Notably, PIK3R1, AKR1C3, and EGFR mRNAs were significantly downregulated in breast cancer tissue, while ESR1 was significantly upregulated." (PMID 39204124, 2024). "Similarly, in our previous in‐silico analysis, HNPMI was found to exhibit bimolecular interaction with EGFR, thereby inducing apoptosis through the EGFR mediated signaling pathway in breast cancer cells." (PMID 37183661, 2024). "Apart from estrogen receptors and HER2, EGFR also plays an important role in breast cancer." (PMID 39100096, 2024). "These datasets included TBCP-1 cells, a mouse HER2-overexpressing breast cancer cell line capable of metastasising to the brain, treated with neratinib for 24 h, and intracranial human EGFR/HER1-mutant TS895 glioblastoma xenograft treated with neratinib for 3 h." (PMID 39002022, 2024). "Expressions of G1/S-phase cell cycle regulators were evaluated alongside EGFR in breast cancer." (PMID 38772416, 2024). "Additionally, CAR-NK cell treatment has been found effective in targeting EGFR and TF in renal cell carcinoma and breast cancer cases, respectively." (PMID 38694508, 2024). "Despite some conflicting functions of TGF-β signaling in different stages of cancer progression 35, previous studies indicated that EGFR-Akt signaling switches TGF-β's function in breast cancer cells from antiproliferation to cancer promotion via EMT induction." (PMID 39309430, 2024).
breast carcinoma (continued). "This suggests that EGFR may be involved in the proliferation and invasion of breast cancer, both of which are characteristics commonly found in high-grade tumors." (PMID 39405290, 2024). "Notably, SPINK1 was found to have the most significant impact on the DFS of breast cancer patients with EGFR gain." (PMID 38892065, 2024). "Although our study partially demonstrated the clinical implications of SUSD2 in EGFR+ HER2+ breast cancer by showing that SUSD2 conferred a poorer survival to EGFR+ HER2+ breast cancer patients and that it was associated with EGFR and HER2 signaling, further mechanistic validation is necessary." (PMID 39791720, 2024). "In addition, in neck and breast carcinoma, EGCG at 30μg/mL EGCG was reported to lower VEGF production in head and neck and breast carcinoma cells by inhibiting epidermal growth factor receptor (EGFR) related pathways." (PMID 38543009, 2024). "The proteomic analysis of SKBR3/HER2+ breast cancer cells treated with the EGFR/ERBB2 receptor Tyr kinase inhibitor Lapatinib and pan-AKT Ser/Thr kinase inhibitor Ipatasertib revealed that the drugs exerted a wide-ranging impact on signaling and biological processes that support cancer progression." (PMID 39268460, 2024). "We also found Rg3 inhibited the glycosylation of PD-L1 in H1299 cells, which also exhibit high level of glycosylated PD-L1.To address how Rg3 affected PD-L1 glycosylation, we noticed that previous researches identified EGFR-GSK3β signaling controls the glycosylation in breast cancer cells." (PMID 39247194, 2024). "Notably, EGFR knockdown in MDA-MB-231 cells reduced GPX4 expression, indicating that EGFR inhibition lowers GPX4 levels in breast cancer cells." (PMID 39881871, 2024). "It has been reported that dacomitinib has effective anticancer activity in various cancers, including EGFR-mutation-positive NSCLC, HER2-positive gastric cancer, HER2-amplified breast cancer, human bladder cancer, and cetuximab-resistant head and neck cancer cell lines." (PMID 38202856, 2024). "Dubba and Koppula synthesized a new series of indole-isoxazole hybrids as EGFR inhibitors; all compounds were evaluated against two breast cancer cell lines, and among this series, two compounds, St.56 and St.57, showed remarkable inhibitory activities against EGFR." (PMID 39404419, 2024). "Anti-EGFR therapies may benefit individuals with EGFR overexpressing breast cancer and could serve as a predictive marker for EGFR targeted treatments." (PMID 39405290, 2024). "As all of these compounds inhibit EGFR protein function, we hypothesised that ORes, similar to these three compounds, facilitates anti-breast cancer activity by inhibiting EGFR." (PMID 39881871, 2024). "The results revealed that the most involved target genes are closely related to cancer pathways, including prostate cancer, proteoglycan in cancer, endocrine resistance, pancreatic cancer, PI3K-AKT signaling pathway, breast cancer, and EGFR tyrosine kinase inhibitor resistance." (PMID 39421674, 2024). "It is a nonreceptor tyrosine kinase overexpressed in more than 60% of breast cancer cases, and EGFR-regulated signaling is impaired in these cancers, which significantly increases MAPK activity and thus leads to fast proliferation and migration of breast cancer cells." (PMID 39598664, 2024). "EGFR overexpression is observed in at least 15% of breast cancers." (PMID 39768978, 2024). "Neratinib is an oral irreversible inhibitor of EGFR/HER1, HER2, and HER4 tyrosine kinases that causes severe diarrhea and presents management issues for antidiarrheal treatment and/or prophylaxis to ensure the continuity of breast cancer treatment." (PMID 38265977, 2024). "In breast cancer, EGFR overexpression correlates with estrogen receptor loss and poor prognosis, suggesting its role in promoting growth in estrogen receptor-positive breast cancer cells, even in the absence of estrogen." (PMID 39194519, 2024).